PGR (progesterone receptor)
Diseases named in the same sentence as PGR in open-access papers (continued):
Sharing a sentence is not in itself a finding about the gene and the disease.
tumor (continued). "In univariate logistic regression models, negative lymph nodes, poor tumour differentiation, negative ER, negative PgR and loss of bcl-2 were found to be significantly predictive of a pCR." (PMID 18380893, 2008). "Positive CA IX was significantly associated with increased overall mortality only in the subgroups of postmenopausal women (P = 0.005), women with one to three positive lymph nodes (P = 0.04), women with ER-positive tumours (P = 0.003) and women with PgR-positive tumours (P = 0.03)." (PMID 18355402, 2008). "Of these, only four considered oestrogen and progesterone receptor status of tumours (ER/PR)." (PMID 18212757, 2008). "Multivariate analysis according to Cox model demonstrated that tumor stage (stage II: relative risk (RR) (confidence interval): 3.46(1.11–10.78); stage III: 7.29(2.37–22.41); p < 0.001) and PgR status (positive: 0.19(0.08–0.49), p < 0.001) were significantly associated with overall survival." (PMID 18507821, 2008). "Neither oestrogen nor progesterone receptor status of the tumours materially influenced the association." (PMID 18594543, 2008). "ER-positive and PgR-positive tumours were found in 56.1% and 39.3%, respectively." (PMID 18380893, 2008). "The present study thus classified ER(−)/PgR(+) tumours as belonging to responsive tumours." (PMID 17726451, 2007). "The tumour factors were the Nottingham Prognostic Index (NPI) calculated from histological grade 1, 2 or 3+Nodal status (no positive nodes=1, 1–3 nodes=2 and >3 nodes positive=3)+0.2 × size of the tumour in cm, oestrogen–progesterone receptor (ER/PR) positivity status and node positivity status." (PMID 17968426, 2007). "Such tumour laterality was significantly associated with Her-2 over expression, but not with ER or PgR expression." (PMID 17892570, 2007). "A significant association between tumour grade and expression of Her-2 (p < 0.0001) and ER (p < 0.0001) but not PgR (p = 0.69) was observed." (PMID 17892570, 2007). "There is some evidence suggesting a worse outcome with tamoxifen for women with ER-positive tumours that lack progesterone receptor (PgR), and/or exhibit overexpression of growth factor receptors such as human epidermal growth factor receptors 1and 2 (EGFR and HER-2/neu)." (PMID 17892469, 2007). "Interestingly, there was a significant association between this type of surgical management and the tumour expression of Her-2, ER, and PgR." (PMID 17892570, 2007). "PGR, which is a direct target of ERα, was also expressed throughout the tumour." (PMID 17573968, 2007). "In addition, immunohistochemical staining of the left breast showed the tumor to be estrogen receptor (ER) (+ve), progesterone receptor (PgR) (+ve) and HER2/neu(-ve)." (PMID 17543123, 2007). "However, there were instances of discordance whereby at both 10–14 days and 3 months, tumours displayed either a phenotype of reduced proliferation but stable PgR or unchanged proliferation and reduced PgR." (PMID 16538221, 2006). "For PgR-positive tumours, there is more uncertainty, but initial use of an AI, for say 3 years, may still be better than sequencing it after 2 years of tamoxifen, as this is the period with highest recurrence rates." (PMID 16434989, 2006). "If PgR is predictive, then initial use of an AI is clearly indicated for PgR-negative tumours." (PMID 16434989, 2006). "Tumor characteristics include stage at diagnosis, grade, ER, and PgR status." (PMID 15987461, 2005). "Another study found a transient increase in risk after first birth mainly in progesterone receptor negative tumours, regardless of oestrogen receptor status." (PMID 15597097, 2005). "Overall, 63.6% of tumours were classified as ER+ and 55.1% were PgR+." (PMID 15611798, 2005).
tumor (continued). "In order to test this hypothesis, we arbitrarily grouped tumours into those with a combination of ‘good’ (ER+ and PgR+, low Ki-67) or ‘bad’ (ER− and PgR− and high Ki-67) biological parameters." (PMID 15611798, 2005). "Only 13 and 25 tumours showed a shift in ER or PgR Allred score of more than 1, respectively." (PMID 15611798, 2005). "However, in multivariate analysis the independent factors compared with non-BRCA1/2 tumours were age, grade and PgR negativity." (PMID 15642173, 2005). "In patients with ER-positive and PgR-positive tumours, a subset likely to be sensitive to the positive benefits of endocrine treatments, a retrospectively derived analysis of the data was suggestive of a possible benefit for fulvestrant compared with tamoxifen in terms of OR." (PMID 15094759, 2004). "When testing these oestrogen-receptor-positive, progesterone-receptor-negative tumours (ER+PR−) in association with uPA–PAI-1 complexes, there appears no increased incidence of nodal invasion." (PMID 12556966, 2003). "Progesterone receptor expression was determined on 99 DCIS tumours in this series." (PMID 12865917, 2003). "We consider that our study could be undersized to detect significant differences, since only 7% of the tumours overexpressed the receptor (n=6) as expected in a sample conformed mostly by ER or PgR positive tumours." (PMID 11870534, 2002). "However, in a multivariate analysis only the number of affected lymph nodes, tumour size, progesterone receptor status, surgical procedure, age and adjuvant tamoxifen therapy retained prognostic significance, whereas the leucocyte nadir count did not." (PMID 10468293, 1999). "Losses of BRCA1 markers correlated with larger tumour size, higher grade, and PgR expression." (PMID 8630282, 1996). "The ER isoforms at pI 6.1 & 6.8 were only found in PgR-positive (> 10 fmol PgR/mg protein) tumours." (PMID 1457348, 1992). "One PgR positive tumour was found to be devoid of PgR by using monoclonal antiPgR antibodies might contain a progesterone binding cyst protein." (PMID 1616860, 1992). "Oestrogen receptor (ER) and progesterone receptor (PR) levels were measured on each tumour." (PMID 2328212, 1990). "Notably, the most common tumor marker expression was estrogen receptor positive (ER+), progesterone receptor positive (PR+), and human epidermal growth factor -2 negative (HER2-), with 14 patients (47%) in the Hispanic group and seven patients (64%) in the non-Hispanic group (p=0.933)." (PMID 40182375, 2025). "Furthermore, regional variations in endometrial gland density and hormonal exposure—particularly differences in estrogen and progesterone receptor distribution—may influence tumor biology and behavior." (PMID 41010688, 2025). "Finally, based on the selection process used, the covariates tumor site, age, numberof radiotherapy sessions, progesterone receptor, Ki-67 protein, HER2 mutation, andmolecular subtype were not included in any of the regression structures." (PMID 40862438, 2025). "Tumor tissue was analyzed at the time of diagnosis and again at the time of definitive surgery for key markers, including the tumor cell proliferation rate (Ki-67 labeling index, the primary endpoint), apoptosis, c-erbB2 expression, and estrogen and progesterone receptor levels." (PMID 40142110, 2025). "One of the rare but clinically especially aggressive variants is the “triple-negative” subtype, i.e. where the tumor cells do not express 3 receptors commonly targeted in hormonal and immunotherapy: estrogen receptor, progesterone receptor, and ERBB2 (HER2) receptor." (PMID 38560553, 2024). "Furthermore, clinical data, such as tumor size, nodal status, clinical stage, and receptors status (i.e., estrogen receptor (ER), progesterone receptor (PR), and human epidermal growth factor receptor 2 (HER2)), were meticulously retrieved from medical records." (PMID 39680357, 2024).
tumor (continued). "We discovered that certain characteristics, like the level of the progesterone receptor in the tumor and whether the cancer had spread to multiple locations or the liver, played a significant role in how long patients benefited from treatment without progression." (PMID 38730711, 2024). "However, the prevalence of Native American genotypes and inherited BRCA mutations within this population can influence not only the incidence of breast cancer but also the estrogen receptor (ER) and progesterone receptor (PR) status, as well as the histology of the tumor." (PMID 39391788, 2024). "Interestingly, in breast cancer, plasma Hsp90 levels did not correlate with primary tumor size or estrogen and progesterone receptor expression, suggesting a specific association with metastatic potential rather than tumor size." (PMID 39594828, 2024). "Overall, these results demonstrated that the well‐established markers (i.e., ESR1, PGR, and MKI67) showed distinct spatial distributions and that the cells included in PNP spots (i.e., ESR1+ and/or MKI67+ cells) were potentially associated with oestrogen‐mediated tumour growth." (PMID 38282415, 2024). "The results in the current study on the tumour models with the cells showing heterogenous gene expression indicated that the expansion of cells expressing typical oestrogen‐regulated genes like PGR would not be directly associated with oestrogen‐mediated proliferation." (PMID 38282415, 2024). "The fact that we observed robust antagonism in CTC174 cells through reduced PGR mRNA expression and tumour growth inhibition at 100 mg/kg, approaching the levels achieved for AZD983337, supported our hypothesis that sufficient compound was penetrating the tumour to bind and antagonise ERα." (PMID 38740899, 2024). "An association between high ezrin expression and ER‐ and PgR‐negative tumours and tumours that were larger, or at a more advanced stage, has also been demonstrated, in addition to an association with lymph node metastasis; a further study has also demonstrated a similar association." (PMID 36938826, 2023). "In addition, low levels of GRB7 expression were associated with lower tumour grade, tumour stage, ER and PgR positive tumours and HER2 negative tumours." (PMID 38036593, 2023). "In addition, low levels of DKK1 expression associated with larger tumours, higher tumour grade, and ER and PgR negative tumours." (PMID 38036593, 2023). "Especially significant correlations of BC glucose metabolism towards histological characteristics of BC regarding estrogen (ER, inverse correlation) and progesterone receptor state (PR, inverse correlation) and tumor aggressiveness (Ki67, verse correlation) could be visualized." (PMID 36980537, 2023). "Indeed, the molecular pathways mediated via ERs and PGR interact together, and the activation of one receptor could influence the activities of the other in neoplastic diseases." (PMID 36263327, 2022). "Hence, our data and results from prior reports suggest that testosterone with AR and ERα could promote CRC development, while E2 and P4, alongside ERβ and PGR, may act as tumour suppressors." (PMID 36263327, 2022). "In addition to the ETV6-NTRK3 gene fusion, PGR, TERT, DOT1L, KDM5A and LRP1B mutations may be passenger mutations that promote tumor progression." (PMID 36585729, 2022). "This may be PgR dependent, as many of those tumours do express low PgR levels." (PMID 35985932, 2022). "Moreover, all cases of NECs were G3 neoplasms, demonstrating larger tumor diameter, higher mitotic and Ki67 index, more frequently positive surgical margins, and lower PgR levels than NETs and non-NENs, all features associated with an aggressive disease." (PMID 36243799, 2022). "The results suggest that people older than 60 years, advanced tumor stage, and estrogen and progesterone receptor-negative patients have higher risk scores (P<0.05), which may represent a poorer prognosis." (PMID 34507558, 2021).
tumor (continued). "CYP27A1 expression was not differentially associated with age, tumor size, ER, PgR, or HER2." (PMID 34556659, 2021). "However, after adjusting for age, race, Carlson comorbidity index, tumor stage, histologic grade, estrogen receptor, progesterone receptor, Her2, radiotherapy, hormonal therapy, and chemotherapy, BMI at baseline was no longer statistically associated with survival outcomes." (PMID 33541403, 2021). "Furthermore, there was a significant correlation between the expression of microRNA —26a and the tumor size, stage, estrogen receptor (ER) and progesterone receptor (PR) status in the HER-2 + group before and after the treatment (p.value = 0.043, 0.042, 0.049 and 0.034 respectively)." (PMID 35223402, 2021). "Moreover, clinical label enrichment analysis and additional tests applied to describe the clusters show good mapping between ClustOmics clusters and key biological clinical labels such as estrogen receptor and progesterone receptor status (ER/PR) or histological type of tumor." (PMID 34229612, 2021). "The PgR as well as ER expression level of the tumor should be considered, as clinicopathological characteristics and patient treatment may vary depending on the HR expression levels of the tumor." (PMID 34638491, 2021). "However, high AR expression is associated with prolonged relapse-free survival, lower grade, and lower number of affected lymph nodes in ERα(+)/PgR(−) BC, thus the mechanistic role of AR and its influence on ERα(+)/PgR(−) tumor aggressiveness requires further studies." (PMID 34638241, 2021). "There are different classification systems based on the tumor’s size, histological subtype grade, lymph node status and expression of different genes, proteins and receptors, such as the estrogen receptor (ER), the progesterone receptor (PR) and the human epidermal growth factor receptor 2 (HER2)." (PMID 33353068, 2020). "High LAIR-1 mRNA expression was associated with higher histological tumour grade, high NPI, Basal and human epidermal growth factor receptor 2 (HER2) enriched PAM50 subtypes and hormone receptor oestrogen receptor (ER) and progesterone receptor (PgR)) negativity (all p < 0.001)." (PMID 33396670, 2020). "With regard to the prognostic factors, the FGFR2 SNP rs1219648 was associated with tumor differentiation (p-value = 0.018), the MAP3K1 SNP rs889312 was linked to the HER2 marker (p-value = 0.04), and the IGF1 SNP rs2373721 was correlated with progesterone receptor status (p-value = 0.04)." (PMID 33112566, 2020). "In addition, we assessed whether the difference in the AR/ER and AR/PgR ratios between primary tumor and metastasis influenced prognosis." (PMID 31110518, 2019). "Similarly, in the CA15-3-high subset, the frequencies of larger tumor size (p < 0.0001), lymph node metastasis (p < 0.0001), ER negativity (p = 0.021), PgR negativity (p = 0.013), HER2 positivity (p = 0.024), and chemotherapy administration (p = 0.0011) were significantly higher." (PMID 29433529, 2018). "In addition, IGF-1 could bind with ER (estrogen receptor) or PR (progesterone receptor) to promote tumorigenesis and tumor growth in breast cancer." (PMID 29162853, 2017). "In this case, the lack of PgR ligands’ actions on tumor cells without PgR might be the cause of altered Ki-67 values." (PMID 28356061, 2017). "Aromatase expression might represent tumor differentiation independent from ER and/or PgR status." (PMID 28489882, 2017). "Increased ERRα levels were associated with ER-negative and PgR-negative tumor status." (PMID 28945747, 2017). "Furthermore, serum TK1 activity was significantly associated with tumor size, lack of ER and PgR, tumor grade, and molecular subtype." (PMID 29162134, 2017).
tumor (continued). "Thus, there might be an association between low ESR1, PGR and PRLR expression and the associated prognosis of the tumor." (PMID 27649560, 2016). "The patient’s evaluation was performed considering different clinical and pathological features such as tumor stage, ER/PgR and Ki-67 level, HER-2 status, age and comorbidities, as commonly done in female BC patients, in order to select those who may benefit from systemic treatment." (PMID 27377827, 2016). "Rs2227928 could be associated with tumour size >2 cm and negative estrogen or progesterone receptor status." (PMID 26920143, 2016). "In the present explorative, and hypothesis generating study, we observed strong positive associations of metabolomic lipoprotein subfractions Apo-A1, HDL, and larger HDL subfractions’ contents of cholesterol, free cholesterol, phospholipids, and apolipoprotein-A1 with tumor PgR expression." (PMID 26970778, 2016). "GATA1/SET7 expression positively associated with tumor size, nodal status and grade, and inversely correlated with the expression of estrogen receptor α (ERα), but they did not associate with age, progesterone receptor (PR) and human epidermal growth factor receptor 2 (HER2)." (PMID 26848522, 2016). "Moreover, SAA-positivity in TAMs was associated with larger tumor-size, higher histological-grade, negative estrogen-receptor and progesterone-receptor statuses, and HER-2 overexpression." (PMID 27058895, 2016). "Thus, further studies of patients with ER+/PgR-/HER2-/ Ki-67 <20% tumours are needed." (PMID 25938238, 2015). "Furthermore, ER+/PgR- tumours expressed higher levels of HER1 and HER2 than ER+/PgR+ tumours." (PMID 25938238, 2015). "Three main tumor subtypes may be determined using traditional immunohistochemistry (IHC); hormone receptor (HR) positive (i.e., estrogen receptor (ER) and progesterone receptor (PR) positive), human epidermal growth factor receptor 2 (HER2) positive, and triple negative tumors." (PMID 25882602, 2015). "Furthermore, nuclear ROCKII activation signal was associated with poor clinical outcome and correlated with late tumor stage, low expression of estrogen receptor (ER) and progesterone receptor (PR), overexpression of human epidermal growth factor receptor 2 (HER2) and high Ki67 labeling index." (PMID 26626121, 2015). "Furthermore, when all NEC and IMC-NOS cases were pooled together, neuroendocrine differentiation itself was an adverse prognostic factor independent of other known prognostic factors, including age, tumor size, nodal status, histologic grade, estrogen/progesterone receptor status, and therapy." (PMID 24589259, 2014). "MMP 3 and MMP 9 were associated with oestrogen and progesterone receptor negative tumours." (PMID 24800085, 2014). "However, trial therapy in the centrally reviewed population was consistently associated with significant multivariate DFS (P = 0.002 to 0.005), in all centrally reviewed patients, and in the subgroup of women whose tumours had positive IHC stain for ER and/or PgR." (PMID 23972025, 2013). "Moreover, FMRP expression is higher in TNBC compared to ER/PgR and/or Her2 positive tumours." (PMID 24092663, 2013). "In sub-analyses stratified for age at diagnosis and prognostic tumour characteristics, elevated CRP levels across tertiles were associated with reduced overall survival irrespective of presence of distant metastases, and estrogen and progesterone receptor status." (PMID 21639875, 2011). "However, when comparing the DSS group with other patients randomised into tAnGo, the DSS group reported a smaller proportion of ER and PgR positive tumours, a larger proportion of HER2 positive tumours, higher nodal status, higher mastectomy rates and worse tumour grades." (PMID 18665163, 2008).